HDAC4 (histone deacetylase 4)
Diseases named in the same sentence as HDAC4 in open-access papers (continued):
Sharing a sentence is not in itself a finding about the gene and the disease.
lung carcinoma (22 papers, 2015 to 2025). "Similarly to our results, NRF2 loss in lung cancer cells decreased HDAC4 and subsequently elevated miR-206." (PMID 29291022, 2017). "In the human lung cancer epithelial-like cell line H1299, deacetylation of 6PGD at K76 and K294 by HDAC4 inactivated its activity." (PMID 39373581, 2024). "The supportive role of HDAC4 in cancer cell metabolic reprogramming, inhibition of HDAC4 sensitizing lung cancer to chemotherapy and radiotherapy 33, 34, all these phenomena support further investigation of HDAC4 as a potential therapeutic target." (PMID 35864951, 2022). "The inhibition of p16INK4A promoter by HDAC3 and HDAC4 has been detected in NCI-H460 lung cancer cells." (PMID 34253688, 2021). "In lung cancer, it has been suggested that an autoregulatory loop including Nrf2, HDAC4, miR-1, and miR-206 may play a key role in the progression of lung cancer." (PMID 39334716, 2024). "miR-520b is able to prohibit lung cancer via regulating HDAC4." (PMID 33758783, 2021). "Likewise, eptoposide resistance in human A549 lung cancer cells was conferred by STAT1-HDAC4 upregulation, and HDAC4 inhibition has been reported to induce apoptosis in non-small cell lung cancer PC-9 cells." (PMID 32641122, 2020). "Interestingly, members of miR-200 family, which are able to revert aberrant histone acetylation in hepatocellular and lung carcinomas by targeting HDAC4, are in turn down-regulated by HDAC4 in an SP1-dependent manner." (PMID 25968566, 2015). "VP-16-resistant lung cancer cells have been shown to display elevated levels of histone deacetylase 4 (HDAC4) and concomitant treatment with both trichostatin A (an HDAC inhibitor) and VP-16 resulted in enhanced cell death in lung cancer cells." (PMID 38398072, 2024). "In lung cancer, ectopic expression of miR-1 reduced the protein levels of MET, Pim-1, FoxP1, and HDAC4 to influence the survival of cancer cells and oncogenic properties." (PMID 28537886, 2017). "It was reported that the treatment with HDAC as an inhibitor of lung cancer cells could induce the expression of repressed miR-1 by the downregulation of oncogenes such as MET, PIM1, FOXP1, and HDAC4." (PMID 37569812, 2023).
Stroke (21 papers, 2013 to 2025). Sudden impairment of blood flow to a part of the brain due to occlusion or rupture of an artery to the brain. "Accumulation of HDAC4 in the nucleus of neurons has been associated with several CNS disorders, including Alzheimer’s disease, stroke, Parkinson’s disease, retinal degeneration, and ataxia telangiectasia." (PMID 35169129, 2022). "Moreover, HDAC4, an epigenetic enzyme, associated to endothelial cell functions and angiogenesis, was linked to ischemic stroke and post-stroke recovery." (PMID 40780200, 2025). "Hdac4 was reported to play a pivotal role in the pathogenesis of ischemic stroke and post-stroke recovery by affecting neuronal death, angiogenesis, and neurogenesis." (PMID 38105266, 2023). "The downregulation of HDAC4 and its relocalization into the neuronal nuclei continued during the recovery period, 2 weeks after stroke." (PMID 34680562, 2021). "Further studies of HDAC4 interactions with different proteins are needed to understand its role in survival and death of cerebral cells after stroke." (PMID 34680562, 2021). "A decrease in HDAC4 expression and its translocation into neuronal nuclei was noted both on the first day, and 2 weeks after stroke." (PMID 34360712, 2021). "First, dysregulated HDAC4 was observed in ischemic stroke, which does play a key role in the pathogenesis of ischemic stroke and post-stroke recovery by affecting neuronal death, angiogenesis, and neurogenesis." (PMID 30208931, 2018). "Accumulated evidence indicates that HDAC4 plays an important role in the post-stroke recovery by modulating neuronal death and synaptic plasticity." (PMID 30208931, 2018). "Increased evidence suggests that histone deacetylase 4 (HDAC4) was dysregulated in ischemic stroke, which plays a key role in the pathogenesis of ischemic stroke and post-stroke recovery by affecting neuronal death, angiogenesis, and neurogenesis." (PMID 30208931, 2018). "The protective mechanism of phosphorylated HDAC4 is associated with HIF-VEGF signaling, implicating a novel therapeutic target in stroke." (PMID 28127553, 2017). "In this study, we report that phosphorylation of HDAC4 was remarkably upregulated after stroke and blockade of HDAC4 phosphorylation with GÖ6976 repressed stroke-induced angiogenesis." (PMID 28127553, 2017). "We detected the phosphorylation of HDAC4 in hypoxia models which mimic the pathophysiology of stroke in vitro." (PMID 28127553, 2017). "Notably, we found that HDAC4 knocking down is neuroprotective when cortical neurons are exposed to an in vitro model of stroke or to environmental neurotoxicants." (PMID 40746867, 2025). "Among the Class II histone deacetylases, HDAC4 expression and phosphorylation are markedly upregulated after stroke, and suppression of HDAC4 phosphorylation inhibits tube formation and the expression of genes downstream of HIF-VEGF signaling in an endothelial cell hypoxia model." (PMID 41403695, 2025). "In addition to HDAC4 expression, nuclear shuttling of HDAC4 is altered in ischemic stroke, which plays an important role in the pathogenesis of stroke and post-stroke recovery." (PMID 30208931, 2018). "Recent studies indicate that HDAC4 is dysregulated in ischemic stroke, which may play a pivotal role in the pathogenesis of ischemic stroke and post-stroke recovery." (PMID 30208931, 2018). "Therefore, we aim to review the dysregulation of HDAC4 in ischemic stroke and the role of HDAC4 in the pathogenesis of ischemic stroke and post-stroke recovery." (PMID 30208931, 2018). "Similarly, the nuclear accumulation of Histone Deacetylase 4 (HDAC4), an epigenetic regulator implicated in several neurodegenerative disorders—including stroke, PD, AD, and ataxia telangiectasia—also disrupts dendrite architecture of mature neurons by negatively affecting VEGFD expression." (PMID 40050849, 2025).
Stroke (continued). "Furthermore, since HDAC1 and 2, belonging to class I HDACs, and HDAC4 and 5, belonging to class II HDACs, increase in an in vitro model of stroke 30, 39, we investigate the specificity of HDAC9, among HDACs isoforms, in the modulation of TfR1 and GPX4 after ODG/Rx." (PMID 37324938, 2023). "Moreover, the nuclear localization of HDAC4 promoted post-stroke brain recovery." (PMID 34680562, 2021). "For instance, DREAM recruits histone deacetylase isoform 4 and 5 (HDAC4 and HDAC5) enzymes, leading to the deacetylation of histone H4 on the promoter of NCX3 gene after stroke." (PMID 37298129, 2023). "Accordingly, both HDAC4 and HDAC5 are predominantly expressed in neurons and increase following stroke injury, especially in neuronal nuclei." (PMID 37298129, 2023). "A recent study showed that the DREAM/HDAC4/HDAC5 complex epigenetically down-regulates ncx3 gene transcription after stroke, and the pharmacological inhibition of class IIa HDACs reduces stroke-induced neurodetrimental effects." (PMID 34360712, 2021). "HDAC4 was highly expressed in the brain, and stroke induced nuclear shuttling of HDAC4 in neurons of the peri-infarct cortex, which did not trigger neuronal cell death, but was positively correlated with neuronal repair after ischemic injury." (PMID 40356977, 2025). "Associated cardiovascular diseases include diabetes (PDLIM5, HDAC4, and TLE1), cardiac development (PDLIM5) and myocardial aging (CASP12), hypertension (PFKP and TAB2), and intracerebral and intraventricular bleeding (RUNX1) and stroke (AXIN2)." (PMID 36620623, 2022). "This indicated that HDAC4 did not participate in the apoptosis of penumbral cells after photothrombotic stroke." (PMID 34680562, 2021). "The HDAC4 level in the cytoplasmic, but not nuclear fraction of the rat brain cortex decreased at 24 h after photothrombotic stroke." (PMID 34680562, 2021). "Histone deacetylase 4 (HDAC4), an enzyme that reduces the acetylation level of histones, is involved in modifying various gene expressions and exerts diverse biological functions; it has been reported as a critical regulator of complex diseases, such as cancers, stroke, and autoimmune diseases." (PMID 35602496, 2022). "However, a direct link between CaMKK signaling and the regulation of HDAC4 translocation in females after stroke has not yet been established." (PMID 25331941, 2014). "During recovery in vivo, stroke induces nuclear shuttling of HDAC4 (but not HDAC5) in neurons localized to the peri-infarct, and increased nuclear HDAC4 is strongly associated with endogenous neuronal repair, suggesting a positive role for HDAC4 in promoting neuronal recovery after ischemic injury." (PMID 28264471, 2017). "Unlike photothrombotic stroke, MCAO induced the nuclear expression of HDAC4 in the mouse cerebral neurons, reduced acetylation of histones 3 and 4, decreased levels of some downstream pro-survival molecules and neuronal death." (PMID 31200484, 2019).
multiple myeloma (20 papers, 2016 to 2025). "For instance, miR-29b, a tumor suppressor, targets HDAC4 and forms a regulatory feedback loop; silencing HDAC4 reduces multiple myeloma cell survival and promotes apoptosis and autophagy." (PMID 40761244, 2025). "For instance, miR-145-3p has been shown to activate autophagy in multiple myeloma cells by direct targeting HDAC4." (PMID 39766786, 2024). "For example, miR-145-3p appears to target HDAC4, promoting autophagy and enhancing bortezomib sensitivity in multiple myeloma." (PMID 38038871, 2024). "Downregulation of HDAC4 increases ATF4 expression under ERS conditions and is associated with increased pro-apoptotic CHOP expression and enhanced apoptosis in multiple myeloma cells." (PMID 38879481, 2024). "Downregulation of HDAC4 increases ATF4 expression under ERS, which is associated with increased pro-apoptotic CHOP expression and enhanced apoptosis of multiple myeloma cells." (PMID 38879481, 2024). "In multiple myeloma (MM), HDAC4 protected cells from ER-stress-mediated apoptosis by repressing activating transcription factor 4 (ATF4)." (PMID 36982651, 2023). "In multiple myeloma, miR-29b mimics reduced HDAC4 expression and myeloma cell migration, while increasing histone H4 acetylation and apoptosis." (PMID 36140219, 2022). "The survival and growth of multiple myeloma is regulated by the HDAC4-RelB-p52 complex, and the disruption of the latter blocks the growth of these cells." (PMID 32641122, 2020). "In multiple myeloma, mir-29b, as a common epimiRNA, can antagonize the carcinogenic effects of high HDAC4 expression." (PMID 30176876, 2018). "On the contrary, overexpression or inhibition of miR-29b, respectively, antagonized or potentiated the anti-myeloma effects of the pan-HDAC inhibitor SAHA confirming that HDAC4-miR-29b axis modulates the effects of anti-myeloma drugs." (PMID 28623912, 2017). "Histone modification is considered an important transcriptional regulatory mechanism and is involved in the progression of multiple tumors, for example, HDAC3-mediated deacetylation leads to ENO2 activation in pancreatic cancer, and the HDAC4-RelB-p52 complex regulates multiple myeloma growth." (PMID 35892859, 2022). "Moreover, in multiple myeloma cells, miR-29b specifically targets HDAC4 mRNA and inhibits HDAC4 expression resulting in the inhibition of cell migration and cell viability and the induction of autophagy." (PMID 31861179, 2019). "Similarly, the upregulation of mir-29b expression will increase the anti-tumor activity of SAHA, confirming the role of the HDAC4-mir-29b axis in regulating anti-myeloma drugs." (PMID 30176876, 2018). "In addition to blocking S100A9, TQ has been previously reported to bind HDAC4 and inhibit its activity; this could be an additional mechanism by which treatment with TQ delayed multiple myeloma progression." (PMID 36923707, 2023). "HDAC IIa composes of HDAC4, HDAC5, HDAC7, and HDAC9, numbers of studies demonstrated HDAC IIa inhibition as an alternative approach to avoid the progression of various diseases, examples like breast tumors, pancreatic cancer, multiple myeloma, and type 2 diabetes." (PMID 35492337, 2022).
amyotrophic lateral sclerosis (18 papers, 2013 to 2025). Amyotrophic lateral sclerosis (ALS) is a neurodegenerative disease characterized by progressive muscular paralysis reflecting degeneration of motor neurons in the primary motor cortex, corticospinal tracts, brainstem and spinal cord. "Hdac4 is an inhibitor of muscle differentiation and increased levels of this protein have been observed after surgical denervation and in models of muscle atrophy associated with amyotrophic lateral sclerosis (ALS)." (PMID 30427927, 2018). "In addition, studies have shown that HDAC4 mediates neural skeletal muscle interactions, and its expression in skeletal muscle is associated with disease severity, which has been proposed as a target for Amyotrophic Lateral Sclerosis (ALS)." (PMID 38148899, 2023). "HDAC4 has already been identified as a molecular target of muscle dysfunction and has been linked to disease progression in amyotrophic lateral sclerosis (ALS) and spinal muscular atrophy (SMA)." (PMID 26668061, 2015). "Patients with amyotrophic lateral sclerosis have high expression of HDAC4 in their skeletal muscles." (PMID 38148899, 2023). "miR-206 regulates HDAC4 via transcriptional repression in amyotrophic lateral sclerosis during innervations." (PMID 35842608, 2022). "In different models of muscle atrophy such as spinal cord atrophy, amyotrophic lateral sclerosis, and Huntington disease, upregulation of the HDAC-4-myogenin axis has been reported, highlighting the central role of this axis on muscle degeneration." (PMID 33375628, 2020). "The role of HDAC4, and its regulator miR-206 in compensatory reinnervation of skeletal muscle and disease progression, have been described in a mouse model of amyotrophic lateral sclerosis (ALS)." (PMID 28420141, 2017). "For example, HDAC4 is negatively regulated by miR-206 in a model of amyotrophic lateral sclerosis, and in a Huntington’s disease model, miR-22 regulates HDAC4." (PMID 28264471, 2017). "HDAC4 up-regulation was significantly greater in patients with rapidly progressive ALS (amyotrophic lateral sclerosis) and was negatively correlated with the extent of muscle re-innervation and functional outcome." (PMID 25748626, 2015). "HDAC4 up-regulation was found to be significantly greater in patients with rapidly progressive ALS (amyotrophic lateral sclerosis) and was negatively correlated with the extent of muscle re-innervation and functional outcome." (PMID 25748626, 2015). "In a mouse model of Amyotrophic Lateral Sclerosis (ALS), the deletion of HDAC4 in skeletal muscle worsens the pathological features of the disease, exacerbating skeletal muscle loss and denervation." (PMID 40332229, 2025). "This has, for example, been shown in amyotrophic lateral sclerosis (ALS), where upregulation of miR-206 has been shown to be part of a cellular autocompensatory mechanism by promoting regeneration at neuromuscular synapses and slowing ALS progression through the downregulation of HDAC4 expression." (PMID 23349832, 2013). "Increased expression of HDAC4 has been detected in skeletal muscle in different diseases, such as Duchenne Muscular Dystrophy (DMD) and Amyotrophic Lateral Sclerosis (ALS): importantly, the observations in pre-clinical models have been validated in patients." (PMID 36901738, 2023).
diabetic nephropathy (17 papers, 2015 to 2025). "To mention, among class II HDACs, HDAC4 has been reported to cause podocyte injury in diabetic nephropathy." (PMID 33096729, 2020). "In this paper, Wnt signaling pathway, Notch-1 signaling pathway and abnormal regulation of HDAC4 and miR-29a all play an important role in podocyte injury in diabetes nephropathy." (PMID 40862124, 2025). "SNHG14 exacerbates diabetic kidney disease by sponging miR-483-5p, thus derepressing HDAC4 and promoting renal tubular damage, inflammation, and fibrosis." (PMID 41463366, 2025). "The expression level of HDAC4 is upregulated in the kidneys of diabetic rats induced by streptozotocin, db/db mice and renal samples from diabetic nephropathy patients." (PMID 39598328, 2024). "In diabetic nephropathy, HDAC4 promotes the deacetylation of signal transduction and transcriptional activator 1 (STAT1), and activated STAT1 inhibits podocyte autophagy, thereby inducing podocyte injury." (PMID 35637410, 2022). "HDAC4 is highly expressed in diabetic nephropathy, which is the main factor of podocyte injury and participates in the progression of diabetic nephropathy." (PMID 35693742, 2022). "The disparity in HDAC4 expression in diabetic nephropathy and cancer suggests its disease-dependent nature." (PMID 33096729, 2020). "The successful in vitro and in vivo delivery of siRNA, as well as targeted gene knockdown potential, was demonstrated by HDAC4 inhibition in vitro diabetic nephropathy (DN) podocyte model as well as in vivo DN C57BL/6 mice model." (PMID 31690769, 2019). "HDAC4 silencing has been proven to attenuate diabetic renal injury, which suggests that pharmacological inhibition of HDAC4 with isoform-selective inhibitor could be a therapeutic option in diabetic nephropathy." (PMID 34071497, 2021). "Our group has previously demonstrated that HDAC4 interference increased the acetylation status of histone H3 at lysine 9 (H3K9Ac), and observed an enrichment of H3K9Ac in the miR-29a proximal promoter in a diabetic nephropathy animal model." (PMID 26305546, 2015). "This axis extends to tissue injury, in diabetic kidney disease, miR-483-5p suppresses TIMP2 and HDAC4, attenuating TGF-β-driven renal fibrosis." (PMID 41463366, 2025). "An early report showed that HDAC4 is highly expressed in podocytes of mice with diabetic nephropathy, whereas knocking down this HDAC isoform with siRNA alleviates podocyte damage in vivo and in vitro, suggesting the importance of HDAC4 in mediating podocyte injury." (PMID 35935816, 2022). "We and others have provided evidence that among class IIa HDACs isoforms, HDAC4 is most commonly expressed in renal tubular cells of a murine model of fibrosis induced by UUO injury and podocytes in a murine model of diabetic nephropathy and human diabetic kidneys." (PMID 35847036, 2022).